SLC30A6 (solute carrier family 30 member 6)
Description:
Has probably no intrinsic transporter activity but together with SLC30A5 forms a functional zinc ion:proton antiporter heterodimer, mediating zinc entry into the lumen of organelles along the secretory pathway. As part of that zinc ion:proton antiporter, contributes to zinc ion homeostasis within the early secretory pathway and regulates the activation and folding of enzymes like alkaline phosphatases and enzymes involved in phosphatidylinositol glycan anchor biosynthesis.
Synonyms: ZNT6; FLJ31101; MST103; MSTP103
Tractability: Antibody: UniProt predicts a signal peptide or a membrane-spanning region. PROTAC: ubiquitination databases record sites on it; its protein half-life has been measured.
Gene: Protein-coding gene on chromosome 2 (32,165,841 to 32,224,379, forward strand). Ensembl gene ENSG00000152683.
Subcellular location: Golgi apparatus, trans-Golgi network membrane; Apical cell membrane
Subcellular location (Human Protein Atlas): Golgi apparatus
Gene Ontology:
Molecular function: protein binding; zinc ion transmembrane transporter activity; zinc:proton antiporter activity; monoatomic cation transmembrane transporter activity
Biological process: regulation of zinc ion transport; zinc ion import into Golgi lumen; zinc ion transport; intercellular transport; monoatomic cation transport; transmembrane transport
Cellular component: Golgi apparatus; trans-Golgi network membrane; transmembrane transporter complex; apical plasma membrane; cytoplasm; membrane
Genetic constraint (gnomAD): Loss-of-function variants: 25 observed, 34.93 expected, observed/expected ratio (o/e) 0.72, 90% interval 0.52 to 1. The upper end of that interval is the gene's LOEUF score, 1, which puts it in group 4 of 6, group 1 being the genes least tolerant of losing a copy. Missense variants: 407 observed, 422.74 expected, observed/expected ratio (o/e) 0.96, 90% interval 0.89 to 1.04. Synonymous variants: 165 observed, 149.59 expected, observed/expected ratio (o/e) 1.1, 90% interval 0.97 to 1.25.
Homologues: Orthologues: chimpanzee SLC30A6 (99% identical), macaque SLC30A6 (98% identical), pig SLC30A6 (95% identical), guinea pig SLC30A6 (95% identical), mouse Slc30a6 (92% identical), rat Slc30a6 (92% identical), dog SLC30A6 (91% identical), rabbit SLC30A6 (89% identical), tropical clawed frog slc30a6 (80% identical), zebrafish slc30a6 (60% identical), Caenorhabditis elegans toc-1 (33% identical). Paralogues in human: SLC30A5 (16% identical), SLC30A3 (16% identical), SLC30A10 (15% identical), SLC30A7 (15% identical), SLC30A1 (15% identical), SLC30A2 (14% identical), SLC30A4 (14% identical), SLC30A8 (14% identical).
Diseases named in the same sentence as SLC30A6 in open-access papers:
SLC30A6 is named in the same sentence as 20 diseases in open-access papers, as found by Europe PMC text mining. Sharing a sentence is not in itself a finding about the gene and the disease. The quoted sentences say what the papers report.
Alzheimer disease (3 papers, 2017 to 2025). A progressive, neurodegenerative disease characterized by loss of function and death of nerve cells in several areas of the brain leading to loss of cognitive function such as memory and language. "Also, increased SLC30A6 (ZnT6) mRNA levels were detected in post-mortem cortex of patients with Alzheimer’s disease." (PMID 28334855, 2017).
prostate carcinoma (3 papers, 2019 to 2024). A carcinoma that arises from epithelial cells of the prostate gland. "Based on the Oncomine database records, the expression of Zn-exporter genes SLC30A1, SLC30A9, and SLC30A10 are upregulated, and SLC30A5 and SLC30A6 are downregulated in prostate cancer compared to BPH." (PMID 36551962, 2022).
cervical cancer (1 paper, 2022). A primary or metastatic malignant neoplasm involving the cervix. "And a high expression of SLC30A1, SLC30A6, SLC30A8 and SLC30A10 was associated with worse overall survival in cervical carcinoma patients." (PMID 35154468, 2022). "For tumor stages, SLC30A1, SLC30A7 and SLC30A10 groups significantly varied, whereas SLC30A2, SLC30A3, SLC30A4, SLC30A5, SLC30A6, SLC30A8 and SLC30A9 did not significantly differ in cervical carcinoma." (PMID 35154468, 2022). "However, the expression of SLC30A3, SLC30A4, SLC30A5, SLC30A6 and SLC30A9 genes in cervical cancer was not statistically significant compared to the corresponding paracancerous tissues." (PMID 35154468, 2022).
gastric adenocarcinoma (1 paper, 2023). "In addition, we found that the expression levels of SLC30A1, SLC30A5, SLC30A6 and SLC30A7 were significantly elevated, while the expression level of SLC30A4 was significantly decreased in gastric adenocarcinoma tissues compared with both normal gastric tissues and matched normal gastric tissues." (PMID 37524874, 2023).
pancreatic adenocarcinoma (1 paper, 2025). "Similarly, SLC30A6 (ZnT6) is significantly upregulated in pancreatic adenocarcinoma and contributes to poor prognosis by promoting cancer cell proliferation via ERK1/2, p38 MAPK, and NF-κB signaling pathways." (PMID 40282424, 2025).
pancreatic cancer (1 paper, 2025). "Among the identified transporters, SLC39A10 and SLC30A6 mediate PDAC-specific zinc metabolic reprogramming, SLC22B5 represents a novel finding in pancreatic cancer, and SLC55A2 is associated with mitochondrial dysfunction and aggressive tumor behavior." (PMID 40282424, 2025).
psoriasis (1 paper, 2021). An autoimmune condition characterized by red, well-delineated plaques with silvery scales that are usually on the extensor surfaces and scalp. "We found the abnormal expression of solute carrier transporter (SLC24A4 and SLC30A6), which may be an important part of mediating metabolic and immune dysfunction in blood dryness syndrome of psoriasis." (PMID 35126107, 2021).
tumor (5 papers, 2009 to 2025). "The differential expression of SLC30A1, SLC30A5, SLC30A6, SLC30A9 and SLC30A10 was found to vary with tumor stage and grade and appears to be related mostly to early events in PCa development and progression." (PMID 27833104, 2016). "Additionally, GSEA highlighted the significant connection of SLC39A10 and SLC30A6 to EMT and other cancer pathways, further supporting their potential as therapeutic targets in PDAC by influencing essential mechanisms of tumor progression." (PMID 40282424, 2025).
SLC30A6 also shares sentences with these, for which no sentence is quoted: cancer (3 papers); Obesity (3); Zinc deficiency (2); acute myeloid leukemia (1); breast carcinoma (1); chronic sinusitis (1); dystonia 1 (1); fragile X-associated tremor/ataxia syndrome (1); immune dysfunction (1); mild cognitive impairment (1); neurodegenerative disease (1); Pick disease (1).